LPAR3 (lysophosphatidic acid receptor 3)
Diseases named in the same sentence as LPAR3 in open-access papers (continued):
Sharing a sentence is not in itself a finding about the gene and the disease.
tumor (continued). "Human HCC were characterized by significantly elevated LPAR1/LPAR3 expression in the microenvironment between the tumor and non-tumor liver (NTL), a finding mirrored in human SKHep1 cells." (PMID 26701886, 2016). "In a seminal murine tumor study examining the overexpression of ATX and LPAR1, LPAR2, and LPAR3 in a mouse mammary tumor virus model, the LPAR2-overexpressing model had the highest tumorgenicity rate at 52.8%, followed by ATX at 50.0%, LPAR3 at 42.3%, and LPAR1 at 32.0%." (PMID 37372960, 2023). "Because autophagic flux significantly decreased in LPAR3 KO cells, LPAR3 signaling may act as an autophagy activator rather than an inhibitor in tumor cells." (PMID 36088312, 2022). "Furthermore, the enhanced expression of LPAR2 and LPAR3, but none of S1PRs, was characteristic for the immune low tumor subtype." (PMID 31049165, 2019). "A cell population in the microenvironment between the tumor and the non-tumor liver, distinct from the tumor mass per se, and expressing LPAR3 and cancer stem cell markers without hepatocyte markers was suggested to mediate tumor invasiveness through a Gαi-ERK pathway." (PMID 31652837, 2019). "Interestingly, the rest of the LPARs (LPAR1, LPAR3–5) are decreased in the HCC liver as compared to adjacent normal tissue, suggesting that LPAR2 and LPAR6 are probably expressed in the tumor whereas the rest LPARs are expressed in the surrounding microenvironment." (PMID 31652837, 2019). "During the course of these studies we reported LPAR1 and LPAR3 expression was increased in a subset of human HCC and cirrhotic non-tumor liver (NTL) compared to liver from non-tumor burdened patients." (PMID 26701886, 2016).
cancer (30 papers, 2004 to 2025). A tumor composed of atypical neoplastic, often pleomorphic cells that invade other tissues. "For example, in triple-negative aldehyde dehydrogenase-positive (ALDH+) breast cancer cells, LPA/LPAR3 induces Ca2+ signalling through the transient receptor potential cation channel subfamily C member 3 (TRPC3) channel to induce cancer stem cell populations." (PMID 38607068, 2024). "LPAR3 is involved in cancer cell migration and invasion, although reports on LPAR3 expression in cancer are inconsistent." (PMID 36088312, 2022). "Conversely, LPAR3 expression is relatively lower in human and mouse cancer cells due to aberrant DNA methylation." (PMID 36088312, 2022). "Although several studies have reported a suppressive role of LPAR3 in carcinogenesis, contradictory reports on LPAR3 promoting cancer progression also exist." (PMID 36088312, 2022). "The aberrant expression of LPA receptors, particularly LPAR2 and LPAR3, has been reported in several cancers, suggesting a significant role for LPA in different cancer types through distinct signaling pathways such as AKT, MAPK, and ERK." (PMID 36551233, 2022). "Because epithelial–mesenchymal transition (EMT) contributes to cancer progression, we quantitatively examined mesenchymal/epithelial markers in parental and LPAR3 KO NIH 3 T3 cells." (PMID 36088312, 2022). "Pharmacological suppression of LPAR3 would suppress motility and invasion in various cancers, including hamster pancreatic cancer cells, human triple-negative breast cancers, fibrosarcoma HT1080 cells, and osteosarcoma HOS cells." (PMID 34209775, 2021). "By screening established human hepatic tumor cells we determined the SKHep1 cell line exhibited a similar profile to the subset of cells that stain positive for both LPAR3 and cancer stem cell markers located at the HCC-NTL margin." (PMID 26701886, 2016). "Given the importance of autophagy in cancer cell survival under stress, it is tempting to speculate that LPA/LPAR3 also regulates autophagy in cancer cells, but this remains to be proven." (PMID 38607068, 2024). "The LPAR3 gene is important in cancer cell proliferation, apoptosis and disease development." (PMID 37727685, 2023). "Interestingly, YAP-S127A was also able to induce LPAR3 expression in immortalized and cancer pancreatic cell lines (S. Y. and J. D., unpublished observations)." (PMID 26440309, 2015). "Epithelial cell (primarily cancer cells) composition was significantly enriched in high-LPAR2 and -LPAR3-expressing tumors in all three cohorts (all p < 0.001) but decreased in high-LPAR1, -LPAR5, and -LPAR6-expressing tumors (all p < 0.05)." (PMID 37372960, 2023). "Former studies have revealed the regulatory function of LPAR3 and EGFR in cancers." (PMID 32231464, 2020). "Lysophosphatidic acid receptor 3 (LPAR3) is one of the G protein-coupled receptors that is specifically triggered by lysophosphatidic acid and is related to proliferation and aggressiveness in certain cancers." (PMID 32724813, 2020). "LPAR3 expression rate is also increased in cancer than in normal specimens, though the difference is not statistically significant (P = 0.275)." (PMID 27809800, 2016). "In addition, the authors found a subset of LPAR3+ cancer stem cells in the same region that might mediate HCC invasion and expansion via LPA-LPAR3 signaling." (PMID 31991677, 2020). "Although Lpar3 expression has not been reported in T cells, it has been reported to mediate motility and proliferation in cancer cells and therefore could play an analogous role in tissue-resident T cells." (PMID 28424687, 2017). "Finally, re-examining human HCC revealed cells staining positive for LPAR3 in the HCC-NTL margin also stained positive for cancer stem cell (but not hepatocyte) markers, features shared by SKHep1 cells." (PMID 26701886, 2016).
cancer (continued). "Analysis of human tissue and human hepatic tumor cells in vitro revealed cells that express LPAR3 (HCC-NTL margin in vivo and SKHep1 in vitro) also express cancer stem cell markers in the absence of hepatocyte markers." (PMID 26701886, 2016). "Significantly, the action of LPA may be more pronounced in GBM cancer stem cells than non-cancer stem cells, as the former show much higher expression of LPAR1 and LPAR3." (PMID 36765904, 2023).
LPAR3 also shares sentences with these, for which no sentence is quoted: cardiac hypertrophy (3 papers); Obesity (3); cervical cancer (2); fibromyalgia (2); myocardial infarction (2); neuroblastoma (2); Pain (2); adenomyosis (1); adrenocortical carcinoma (1); Anxiety (1); bacterial infection (1); benign ovarian tumors (1); bone cancer (1); chronic leukemia (1); diabetic (1); diabetic neuropathy (1); female infertility (1); female reproductive cancers (1); glioma (1); hematological disorders (1); Hydrocephalus (1); Hypertension (1); infarction (1); infection (1); ischemia (1); lung adenocarcinoma (1); lung fibrosis (1); lymph node metastases (1); medullary carcinoma (1); mesothelioma (1).
A further 17 diseases each share a sentence with LPAR3 in 1 paper.